CYP4F22 (cytochrome P450 family 4 subfamily F member 22)
Description:
A cytochrome P450 monooxygenase involved in epidermal ceramide biosynthesis. Hydroxylates the terminal carbon (omega-hydroxylation) of ultra-long-chain fatty acyls (C28-C36) prior to ceramide synthesis. Contributes to the synthesis of three classes of omega-hydroxy-ultra-long chain fatty acylceramides having sphingosine, 6-hydroxysphingosine and phytosphingosine bases, all major lipid components that underlie the permeability barrier of the stratum corneum. Mechanistically, uses molecular oxygen inserting one oxygen atom into a substrate, and reducing the second into a water molecule, with two electrons provided by NADPH via cytochrome P450 reductase (CPR; NADPH-ferrihemoprotein reductase).
Synonyms: FLJ39501; ARCI5; INLNE; LI3
Tractability: Small molecule: it belongs to a druggable protein family. Antibody: UniProt predicts a signal peptide or a membrane-spanning region. PROTAC: ubiquitination databases record sites on it.
Gene: Protein-coding gene on chromosome 19 (15,508,477 to 15,552,317, forward strand). Ensembl gene ENSG00000171954.
Subcellular location: Endoplasmic reticulum membrane; Microsome membrane
Pathways (Reactome):
Metabolism: Eicosanoids; Fatty acids; Miscellaneous substrates; Synthesis of Leukotrienes (LT) and Eoxins (EX)
Disease: Defective CYP4F22 causes ARCI5
Gene Ontology:
Molecular function: monooxygenase activity; protein binding; heme binding; iron ion binding; oxidoreductase activity, acting on paired donors, with incorporation or reduction of molecular oxygen
Biological process: ceramide biosynthetic process; icosanoid metabolic process
Cellular component: endoplasmic reticulum membrane
Genetic constraint (gnomAD): Loss-of-function variants: 37 observed, 63.58 expected, observed/expected ratio (o/e) 0.58, 90% interval 0.45 to 0.77. The upper end of that interval is the gene's LOEUF score, 0.77, which puts it in group 3 of 6, group 1 being the genes least tolerant of losing a copy. Missense variants: 655 observed, 748.24 expected, observed/expected ratio (o/e) 0.88, 90% interval 0.82 to 0.93. Synonymous variants: 258 observed, 292.94 expected, observed/expected ratio (o/e) 0.88, 90% interval 0.8 to 0.98.
Homologues: Orthologues: chimpanzee CYP4F22 (99% identical), macaque CYP4F22 (97% identical), dog CYP4F22 (92% identical), rabbit CYP4F22 (90% identical), pig CYP4F22 (89% identical), rat Cyp4f39 (87% identical), mouse Cyp4f39 (87% identical), guinea pig CYP4F22 (85% identical), tropical clawed frog cyp4f22 (62% identical), Drosophila melanogaster Cyp4c3 (32% identical), Drosophila melanogaster Cyp4d2 (31% identical), Drosophila melanogaster Cyp4s3 (30% identical), and 25 more. Paralogues in human: CYP4F2 (63% identical), CYP4F3 (63% identical), CYP4F11 (62% identical), CYP4F12 (61% identical), CYP4F8 (59% identical), CYP4A11 (41% identical), CYP4A22 (40% identical), CYP4B1 (40% identical), CYP4X1 (37% identical), CYP4Z1 (35% identical), CYP4V2 (33% identical), CYP19A1 (21% identical).
Diseases named in the same sentence as CYP4F22 in open-access papers:
CYP4F22 is named in the same sentence as 28 diseases in open-access papers, as found by Europe PMC text mining. Sharing a sentence is not in itself a finding about the gene and the disease. The quoted sentences say what the papers report.
ichthyosis (17 papers, 2012 to 2026). Disorders of cornification that are characterized by visible scaling and/or hyperkeratosis of most or all of the skin. "Exome sequencing followed by segregation analysis identified pathogenic variants in four established ichthyosis-associated genes: CYP4F22, FLG, ALOX12B, and NIPAL4." (PMID 42196615, 2026). "In an Italian cohort study, 16.2% of patients with congenital ichthyosis had a mutation in the CYP4F22 gene locus." (PMID 40858268, 2025). "Mutations in the CYP4F22 gene locus have been previously identified in Italian, Spanish, and Chinese patients with congenital ichthyosis." (PMID 40858268, 2025). "Since CYP4F22 has only recently drawn attention for its involvement in congenital ichthyosis, a rise in identified mutations is to be expected which will also lead to more thorough structural and functional studies of this important key player in skin health." (PMID 40858268, 2025). "Before this, CYP4F22 had been known since 2006 to be associated with the skin disease lamellar ichthyosis, which ultimately led to the quest to unravel CYP4F22 function." (PMID 40858268, 2025). "In 2019, a more detailed theory of lamellar ichthyosis based on a missense mutation in exon 8, CYP4F22 Arg243Leu, was predicted to be a functionally defective variant via in silico analysis." (PMID 36902463, 2023). "Six years later, mutations on a new gene FLJ39501, which encodes CYP4F22 (cytochrome P450, family 4, subfamily F, polypeptide 22), were found in 21 patients with autosomal recessive congenital ichthyosis, in four countries." (PMID 36902463, 2023). "We report the case of a patient who was heterozygous for a pathogenic variant and a variant of uncertain significance in the CYP4F22 gene and presented with a collodion membrane and developed a mild ichthyosis phenotype." (PMID 35350521, 2022). "Patient C‐II‐2 and her brothers, C‐II‐3, 4, and 5, showed ichthyosis, which was due to a known mutation of CYP4F22 (c.728G>A, p.Arg243His) that was also identified on exome analysis of patient C‐II‐1." (PMID 31876103, 2020). "Since the discovery of CYP4F22 was linked to its association with lamellar ichthyosis, genetic studies of CYP4F22 polymorphisms have been undertaken." (PMID 31480463, 2019). "A CYP4F22 variant, CYP4F22 Arg243Leu, was associated with lamellar ichthyosis in a Tunisian family, and further genetic studies should be conducted in clinical settings." (PMID 31480463, 2019). "These latter two patients had lamellar ichthyosis caused by a CYP4F22 mutation and Netherton syndrome, respectively (for these patients, the VAS erythema was reduced by 4 and 5 points, respectively)." (PMID 29618363, 2018). "Large decreases in or loss of acylceramide due to mutations in the genes involved in acylceramide synthesis (such as CERS3, CYP4F22 and ELOVL4) causes non-syndromic ARCI (CERS3 and CYP4F22) or a syndromic form of ichthyosis (ELOVL4) (refs 5, 8, 10, 12, 21)." (PMID 28248318, 2017). "Therefore, it appears that epidermal damage in people with ichthyosis is related to CYP4F22 deficiency." (PMID 38621674, 2024). "Since the discovery that CYP4F22 is one of the causative genes for ichthyosis, the molecular mechanisms underlying the role of CYP4F22 in the etiology of ichthyosis have remained largely unknown until recently." (PMID 31480463, 2019). "CYP4F22 is one of the autosomal recessive genes for congenital ichthyosis, and lipid studies in patients with ichthyosis have revealed that acyl ceramide formation in the skin is substantially decreased in these individuals (Ref." (PMID 38621674, 2024). "Accordingly, humans carrying mutant alleles of ELOVL4, CYP4F22, or CERS3 develop a similar ichthyosis pathology as reported for ABHD5 and PNPLA1 deficiency due to the lack of ULC ω-hydroxy ceramides and AcylCer in the epidermis." (PMID 30361410, 2018). "To date, multiple genes have been shown to be associated with ichthyosis, including ALOXE3, ALOX12B, TGM1, CYP4F22, NIPAL4, and ABCA12." (PMID 24278723, 2012).
ichthyosis (continued). "In the literature, there are several reports of homozygous or compound heterozygous missense mutations in CYP4F22 leading not only to SHCB but also to lamellar ichthyosis, a nonimproving ARCI phenotype." (PMID 36332686, 2022). "Ten patients suffered from congenital ichthyosis, seven of them having lamellar ichthyosis (Ichthyn: n 4, CYP4F22: n 1, TGM1: n 1, ongoing analysis: n 1) and three cases of congenital ichthyosiform erythroderma (two patients who carried ABCA12 mutations, and one who had no identified mutation)." (PMID 29618363, 2018). "There are 6 genes currently known to be associated with ichthyosis: ALOXE3, ALOX12B, TGM1, CYP4F22, NIPAL4, and ABCA12, and although thought to be unrelated, both the probands from family 1 and family 2 harboured an identical novel missense variant, c.G4676T, p.Gly1559Val in ABCA12." (PMID 24278723, 2012).
autosomal recessive congenital ichthyosis (12 papers, 2012 to 2025). Autosomal recessive form of inherited ichthyosis. "CYP4F22 has been identified as a causative gene of autosomal recessive congenital ichthyosis (ARCI)." (PMID 36332686, 2022). "CYP4F22 deficiency belongs to the group of autosomal recessive congenital ichthyosis (ARCI), which is a heterogeneous collection of rare disorders of keratinization characterized by generalized abnormal scaling of the skin." (PMID 38693715, 2025). "Based on clinical examination and genetic testing, a diagnosis of SICB was confirmed, with mutations identified in genes commonly associated with autosomal recessive congenital ichthyosis, such as ALOX12B, TGM1, ALOXE3, CYP4F22, and PNPLA1." (PMID 40193669, 2025). "Mutations in CYP4F22 cause autosomal recessive congenital ichthyosis (ARCI)." (PMID 32069299, 2020).
keratoderma (2 papers, 2016 to 2022). "ALOX12B and CYP4F22 mutations usually produce moderate keratoderma." (PMID 26762237, 2016). "Our findings showed that palmoplantar keratoderma was associated with NIPAL4, TGM1, CYP4F22 mutations and CERS3 deletion, but with varying severity." (PMID 34983512, 2022).
acute myeloid leukemia (1 paper, 2018). Acute myeloid leukemia (AML) is a group of neoplasms arising from precursor cells committed to the myeloid cell-line differentiation. "In this regard, CYP4F22 overexpression may function similar to the acid ceramidase gene (AC), overexpressed in multiple tumor types, and increasingly recognized as an important therapeutic target for pediatric brain tumors, acute myeloid leukemia, and melanoma." (PMID 30093970, 2018).
erythroderma (1 paper, 2022). "Commonly, ARCI presents with a taut, thick, shiny stratum corneum called a collodion membrane, but patients with mutations in CYP4F22 frequently present only with erythroderma." (PMID 35350521, 2022).
hepatocellular carcinoma (1 paper, 2018). A malignant tumor that arises from hepatocytes. "The Cancer Genome Atlas links CYP4F22 overexpression to hepatocellular carcinomas (found in ∼60% of samples tested) and tumors of the bladder, breast and ovaries, however its role in cancer progression remains unclear." (PMID 30093970, 2018).
Hypertension (1 paper, 2020). The presence of chronic increased pressure in the systemic arterial system. "Nonetheless CYP4F22 and CYP4F2 are described as paralogs and genetic variants in the CYP4F2 were associated with hypertension." (PMID 32425885, 2020).
hypertensive nephropathy (1 paper, 2020). Kidney damage that results from chronically elevated blood pressure; complications include glomerular damage resulting in proteinuria and hematuria. "We observed decreased expression of CYP4F22 mRNA in the decliner group; downregulation of CYP4A11 mRNA, another CYP4 isoform involved in 20-HETE generation, was already described in a gene expression profile of renal biopsies from patients with hypertensive nephropathy." (PMID 32425885, 2020).
lamellar ichthyosis (1 paper, 2019). A keratinization disorder characterized by the presence of large scales all over the body without significant erythroderma. "Genetic screening for CYP4F22 mutations associated with lamellar ichthyosis should be extended in future works." (PMID 31480463, 2019). "Recently, a CYP4F22 genetic variant associated with lamellar ichthyosis was reported in a Tunisian family." (PMID 31480463, 2019). "A missense mutation in exon 8, CYP4F22 Arg243Leu, was suggested to be linked to lamellar ichthyosis and predicted to be a functionally defective variant based on in silico analysis." (PMID 31480463, 2019).
Obesity (1 paper, 2013). Accumulation of substantial excess body fat. "Though not significant, suggestive AM associations included LPL and CYP4F22, which are associated with type 2 diabetes and lipid metabolism (rs1372339, rs4922116, rs1273516), and TMEM18 (rs2947411), associated with obesity and body mass index." (PMID 23424626, 2013).
Palmoplantar hyperkeratosis (1 paper, 2019). Abnormal thickening of the skin localized to the palm of the hand and the sole of the foot. "Furthermore, all Saudi Arabian patients showed palmar hyperlinearity but only TGM1 and ABCA12 affected individuals presented palmoplantar hyperkeratosis, while NIPAL4 and CYP4F22 presented only plantar keratosis." (PMID 30600594, 2019).
psoriasis (1 paper, 2016). An autoimmune condition characterized by red, well-delineated plaques with silvery scales that are usually on the extensor surfaces and scalp. "Genes controlling abnormal keratinocyte differentiation and epidermal barrier function (CYP4F22, SULT2B1) were up-regulated in psoriasis." (PMID 26901218, 2016).
steatosis (1 paper, 2024). Increased lipid within the cytoplasm of cells. "In human patients, the CYP4F12, CYP4F22, and CYP4V2 mRNA levels increase in steatosis and MASH, while the levels of CYP4B1, CYP4X1, and CYPZ1 mRNAs decrease in steatosis and MASH while the mRNA for these genes increases in HCC." (PMID 40452921, 2024).
carcinoma (3 papers, 2018 to 2022). A malignant tumor arising from epithelial cells. "We hypothesize that CYP4F22 overexpression may function to regulate the accumulation of pro-apoptotic sphingolipids (e.g. ceramide) in cancer cells, which similar to RBM11, promote alternative splicing of the BCL-XS splice variant." (PMID 30093970, 2018). "It is also notable that we identified over 10 cancer-related genes (including PHGDH, CCND1, IGFBP-2, XAGE1B/E, CYP4F22, RBM11, ORAOV1, MDK, UGT3A5, SSX5, FBL, NKX2) potentially overexpressed in EFT tumors." (PMID 30093970, 2018). "According to the correlation between the predictive expression of 7 metastasis-related lncRNAs and the OS of ccRCC patients from TCGA database, the expression of SSR3-6, WISP1-2, CYP4F22-3 and UBAC2-6 were identified in carcinoma and adjacent tissues of ccRCC patients (normal=9, tumor=9)." (PMID 34150667, 2021). "Mechanistic insights are still required to explain the cytotoxic effects we observed, but the identification of RBM11, CYP4F22 and IGFBP-2 as new potential drug targets for EFT would seem to confirm the utility of this open source, computational methodology for cancer drug discovery." (PMID 30093970, 2018). "This transcriptome profiling approach is highly effective for cancer drug discovery, as it identified new EWS-specific target genes (e.g. CYP4F22, RBM11 and IGBP-2), and predicted effective antisense agents (EC50 < 1 μM) that demonstrate both synergy and antagonism in combination therapy." (PMID 30093970, 2018). "In the IHC data of HPA, there is a lack of carcinoma or corresponding normal tissues of several candidate genes includingSDR9C7,RDH12,RAET1E,CERS3,PLA2G4E,CYP4F22, andDENND2C." (PMID 36017889, 2022).
tumor (3 papers, 2018 to 2022). "Only two genes (GPER1 and CYP4F22) were oppositely correlated with SETD7 expression in different subtypes, being enriched in in low-SETD7 tumours for all subtypes except luminal B where they were upregulated in the high-SETD7 group." (PMID 36551516, 2022). "Despite limitations to this approach, we have identified several single agents that are highly cytotoxic to EFT cells, and morpholino cocktails targeting PHGDH transcripts, in combination with XAGE1 or CYP4F22, may be highly synergistic across multiple EFT tumor types." (PMID 30093970, 2018).
inherited diseases (1 paper, 2020). "Similar to other genes associated with inherited diseases, large deletions have been found among the ALOX12B and CYP4F22 disease alleles." (PMID 33255364, 2020).
CYP4F22 also shares sentences with these, for which no sentence is quoted: congenital ichthyosis (3 papers); brain tumors (1); congenital ichthyosiform erythroderma (1); dementia (1); Erythema (1); melanoma (1); Netherton syndrome (1); non-bullous congenital ichthyosiform erythroderma (1); palmoplantar keratoderma (1); pustular psoriasis (1); tumors of the bladder (1); type 2 diabetes (1).